BRD9 (bromodomain containing 9)
Diseases named in the same sentence as BRD9 in open-access papers (continued):
Sharing a sentence is not in itself a finding about the gene and the disease.
cancer (continued). "Bromodomain-containing protein 9 (BRD9) belongs to the chromatin remodeling/sucrose non-fermentable (SWI/SNF) switch complex, which interacts with chromatin and transcription factors involved in cell proliferation, apoptosis, differentiation, and cancer." (PMID 38994959, 2024). "BRD9 is a non-BET bromodomain-containing protein that maintains and facilitates oncogenic transcription directly by recognizing the acetylated lysine on post-translationally modified histone proteins, contributing to cancer cell proliferation and survival." (PMID 32457312, 2020). "Although the result of immunofluorescence indicated that the protein levels are high in cancers, whether the protein levels are increased with the amplification of the copy number of ACTL6A or BRD9 is still not clear (p value>0.05)." (PMID 31504061, 2019).
tumor (65 papers, 2016 to 2026). "Tumor sphere assay revealed a reduction of spheres in both cell lines by 2 different short hairpin RNA (shRNA) constructs, indicating that BRD9 loss-of-function via KD phenocopies the reduction of CSC self-renewal as seen with chemical inhibition of BRD9." (PMID 37739089, 2024). "Recently, some publications have provided experimental evidence that elevated expression of BRD9 has been linked to the progression of tumours." (PMID 38303608, 2024). "Mutant SF3B1 recognizes an aberrant branchpoint within BRD9, which promotes the recognition of a poison exon and subsequent degradation of BRD9 mRNA, resulting in the loss of tumor-suppressing activity." (PMID 36833284, 2023). "Given that rhabdoid tumor cell lines are susceptible to BRD9 inhibition, we sought to investigate the direct targets of BRD9 in mock-treated cell lines (which model the cancerous state) by ChIP-seq." (PMID 34071089, 2021). "Positive staining of the BRD9 protein in HCC tissues was associated with a tumor size ≥ 5 cm (P = 0.027), the occurrence of vascular infiltration (P = 0.003), and an advanced TNM stage (P = 0.003)." (PMID 32908135, 2020). "The findings showed that ‘axon guidance’ and ‘spliceosome’ could potentially be implicated in the influence of BRD9 on tumour progression." (PMID 38303608, 2024). "The methylation of the BRD9 gene was associated with tumor stages II and tumor size <5 cm." (PMID 35359376, 2022). "Targeting BRD9 abolished PCa colony formation and migration in vitro, and inhibited orthotopic tumor growth in vivo." (PMID 41980921, 2026). "In this dataset, the expression of BRD9 was lower in biphasic tumor cells (Biphasic_glands and Biphasic_spindled) compared to monophasic and poorly differentiated cells." (PMID 41440042, 2025). "Our study provides novel insights into the multilayered regulation of key EMT players by SS18::SSX and BRD9 in SySa, thereby defining tumor phenotype and (potentially) prognosis." (PMID 41440042, 2025). "Given the observed regulatory effects of BRD9 (GBAF) on EMT/MET pathways, we further investigated the potential correlations between BRD9 and cellular differentiation in human SySa tumor samples." (PMID 41440042, 2025). "Recent studies, such as Muran Xiao's research, have demonstrated that chromatin remodeling components like BRD9 influence stem cell differentiation and tumor progression." (PMID 39757177, 2025). "Here, we identified Bromodomain-containing protein 9 (BRD9) as a metabolic checkpoint for reprogramming cell metabolism to support tumor growth and impart a castration-resistant phenotype under metabolic and oxidative stress." (PMID 40263302, 2025). "Analysis of survival data and DNA methylation for BRD9 indicated distinct conclusions for multiple tumours." (PMID 38303608, 2024). "Although BRD9 inhibition suggested tumor progression through regulating PDAC cell growth in our cell-line xenografts, the cell-line xenografts do not accurately recapitulate the histopathological and molecular characteristics of the human parental tumor." (PMID 37739089, 2024). "We then integrated all tumour expression data from TCGA to determine the top 100 genes that exhibited a correlation with BRD9 expression." (PMID 38303608, 2024). "To study the impact of BRD9 inhibition on CSC self-renewal capacity, we performed tumor sphere assays with 3 different BRD9 inhibitors (I-BRD9, TP-472, and dBRD9) in 5 different PDAC cell lines and primary cells from surgically resected PDAC tumors." (PMID 37739089, 2024). "Transcriptomic analysis of BRD9 inhibition suggests roles for ncBAF in cell-cycle progression, myeloid differentiation, and suppression of tumor suppressor genes." (PMID 38126767, 2024). "Since BRD9 is also involved in the regulation of chromatin remodeling and gene expression, it significantly impacts the proliferation and survival of tumor cells." (PMID 39124901, 2024).
tumor (continued). "For instance, small‐molecule inhibitors of the BRD9 bromodomain effectively attenuate tumor cell proliferation and survival and induce apoptosis." (PMID 35778964, 2023). "Taken together, our findings revealed that BRD9 expressed highly in tumor versus normal tissues, which functions as a prognostic factor in COAD." (PMID 35778964, 2023). "Firstly, we downloaded the mRNA expression matrix of BRD9 from the TCGA‐COAD cohort, and observed that BRD9 expressed highly in tumor samples versus normal tissues with p < 0.001." (PMID 35778964, 2023). "In kidney cancers, BRD9 promoted tumor malignancy by activating the Notch signaling pathway in HIF-2a tumors." (PMID 36674511, 2023). "BRD9 expressed highly in tumor samples versus normal adjacent tissues and patients with high BRD9 suffered from worse survival outcomes compared with those with low BRD9." (PMID 35778964, 2023). "The anti-tumor effects of TP-422 were associated with changes in the expression of extracellular matrix and apoptotic genes, suggesting that either BRD7 or BRD9 or both promote tumor growth and invasiveness." (PMID 35323214, 2022). "Mutations in the splice factor SF3B1/SAP155 affects the formation of BRD9 in the ncBAF complex and this changes transcriptional output and promotes tumour growth." (PMID 35187582, 2022). "The BRD9-targeting ASO was also shown to be effective in tumor suppression in rectal melanoma patient-derived xenografts." (PMID 34899861, 2021). "Knockdown of BRD9 also resulted in tumor growth, augmented melanocyte pigmentation, and decreased expression of melanocyte lineage specific genes in Melan-a cells." (PMID 34899861, 2021). "Excitingly, ASOs designed to block the inclusion of the BRD9 poison exon was sufficient to rescue mis-splicing, increase protein levels, and suppress tumor growth in both UVM cells and mice xenografted with UVM cells." (PMID 34899861, 2021). "KAT2A, SP140 and BRD9 protein expression was higher in tumor tissues, and SMARCA2, BRPF3, KAT2B and EP300 protein expression was lower in the tumor tissues." (PMID 34149798, 2021). "It has also been shown that MiR-140-3p (a tumour-suppressive miRNA) targets BRD9 mRNA, downregulating MYC and reducing proliferation." (PMID 34944438, 2021). "The data from the TCGA database and 5 GEO datasets consistently demonstrated that the expression of BRD9 in HCC tissues was significantly higher than that in non-tumor liver tissues (P < 0.05)." (PMID 32908135, 2020). "The tumor volume in the BRD9 knockdown group was significantly decreased compared with that in the control group (P < 0.05)." (PMID 32908135, 2020). "Correction of BRD9 mis-splicing restored tumor suppressor activity of BRD9, as well as mRNA and protein levels, revealing a promising route for future research into BRD9 mis-splicing-targeted therapies." (PMID 33143733, 2020). "The results of Ki67 staining demonstrated that tumor tissues from the BRD9 knockdown group exhibited a decreased percentage of Ki67-positive cells than those from the control group (P < 0.05)." (PMID 32908135, 2020). "The qRT-PCR assay showed that compared with adjacent non-tumor tissues, the level of BRD9 mRNA in HCC tissues was significantly elevated (P < 0.05)." (PMID 32908135, 2020). "Next, we confirmed that the expression of BRD9 was increased in HCC tissues compared with that in adjacent non-tumor tissues." (PMID 32908135, 2020). "In an attempt to correct mis-splicing of BRD9, specific ASOs were employed both in vitro and in vivo, which showed satisfactory results in splicing modulation and suppressing tumor growth." (PMID 32481522, 2020). "Nuclear staining of BRD9 protein was detected in more than 90% of tumor specimens, which is consistent with its predicted nuclear function." (PMID 30760718, 2019). "Degradation of BRD9 induces downregulation of oncogenic transcriptional programs and inhibits tumour progression in vivo." (PMID 30431433, 2018).
tumor (continued). "Overall, our findings indicate that tumor cell-intrinsic BRD9 orchestrates metabolic reprogramming and that BRD9 ablation may be a viable avenue for improving the effectiveness of radiotherapy." (PMID 40263302, 2025). "Importantly, BRD9 inhibitor (I-BRD9) synergized with enzalutamide to inhibit cell proliferation and delay tumor growth." (PMID 40263302, 2025). "Importantly, BRD9-KD further delayed tumor growth compared with A13AlNull and A13Agemcitabine groups." (PMID 37739089, 2024). "This specific dependency on BRD9 for AML cell growth may be perpetuated through the CCR2-CCL2 tumor proliferation axis." (PMID 38126767, 2024). "Our study revealed that BRD9 exhibited elevated expression in a wide range of tumours." (PMID 38303608, 2024). "Intriguingly, BRD9 also appears to exert a significant role in tumor suppression." (PMID 35778964, 2023). "High BRD9 promotes the proliferation and migration of tumor cells." (PMID 35778964, 2023). "Moreover, several novel BRD inhibitors, including I-BRD9, BI-7273, and BI-9564, can specifically target BRD9 and possess anti-tumor activity." (PMID 35419278, 2022). "When mis-splicing of BRD9 in SF3B1-mutated cells was corrected, tumor growth was suppressed." (PMID 33333932, 2020). "Indeed, tumor-suppressive effects of correcting BRD9 mis-splicing with multiple methods, including antisense oligonucleotides, were achieved." (PMID 32188117, 2020). "Furthermore, we showed for the first time that by negatively regulating SOCS3 expression, BRD9 in turn influences activation of the tumor-driver STAT5 pathway, affecting leukemic cell proliferation and survival." (PMID 31000698, 2019). "Collectively, our results demonstrate that genetic depletion of BDR9 expression significantly represses tumor cell growth in vitro and in vivo, suggesting that small molecular compounds targeting BRD9 may have strong clinical application potentials." (PMID 30760718, 2019). "We hypothesized that inhibition of aberrant SWI/SNF function by selective blockade of the BRD9 subunit of the SWI/SNF complex would reduce tumor cell proliferation." (PMID 28714904, 2017). "Therefore, given that the biological roles of BRD9 become clear in tumor progression, targeting the bromodomain of BRD9 could provide a novel and attractive tumor treatment selection." (PMID 35778964, 2023). "However, depletion of BRD9 significantly delayed tumor growth following olaparib treatment." (PMID 32457312, 2020). "In addition, the amplification of ACTL6A and BRD9 commonly occurred in multiple cancers and may play crucial roles in tumor formation." (PMID 31504061, 2019). "BRD9 overexpression in both ULM and ULMS further supports the concept of a progressive epigenetic continuum between the two tumor types." (PMID 40867239, 2025). "Similar to BRD4, BRD9 also belongs to the BRD family, and its role in tumor development is gaining special attention." (PMID 39124901, 2024). "Taken together, these data revealed that BRD9 activates transcriptions of ALDOC and ENO2 to enhance glycolytic metabolism and tumor progression in COAD." (PMID 35778964, 2023). "In ICC samples, the expression value of HBV-integrated genes, including MET, WNT2, BRD9, and TERT, in tumor seems to be higher than the paired non-tumor tissues." (PMID 36123506, 2022). "To further validate the data from online databases, we quantified the expression of BRD9 in 110 pairs of HCC specimens and adjacent non-tumor liver tissues." (PMID 32908135, 2020). "This is also supported by CRISPR-Cas9-based screens, identifying BRD9, GLTSCR1 and BAF60A, all being subunits of the ncBAF complex, as critical for rhabdoid tumour cell line survival." (PMID 30898143, 2019). "When castrated mice bearing C4-2B with BRD9 overexpression or not were treated with CP-320626, the BRD9-induced increase of tumor growth was significantly inhibited, as shown by tumor growth, tumor volume, and the proliferation index Ki67." (PMID 40263302, 2025).
tumor (continued). "Notably, Bromodomain-containing protein 9 (BRD9) is frequently overexpressed in HCC, which reportedly upregulates the Wnt/β-catenin and TUFT1/AKT pathways, enhancing tumor aggressiveness and correlating with poorer patient prognosis." (PMID 40057667, 2025). "As expected, gemcitabine (Gem), BRD9 inhibitor (IBRD9), or gemcitabine in combination with BRD9 inhibitor (IBRD9 + Gem) significantly delayed the tumor growth as evidenced by the tumor growth curves and tumor volume when compared with DMSO-treated control group (Ctrl)." (PMID 37739089, 2024). "We observed a positive correlation between BRD9 expression and the estimated number of CAFs in TCGA tumours of COAD, HNSC and HNSC‐HPV−, but conversely, a negative correlation was observed in LGG." (PMID 38303608, 2024). "BRD9 inhibitors strive for specificity, meaning they target the BRD9 protein, minimizing the impact on other bromodomain proteins that could have an opposite effect, such as BRD7, which has tumor-suppressive functions." (PMID 38543178, 2024). "Furthermore, new research identifying an antagonistic relationship between BRD9 and LDS1 provides a compelling basis for future exploration of GBAF tumor suppressor function." (PMID 33143733, 2020). "For instance, BRD9 has been identified as a subunit of the mammalian SWI/SNF chromatin remodelling complex involved in organismal development, gene regulation, and cell lineage specification, which seems to be involved in tumour suppression." (PMID 32276436, 2020). "BRD9 KD did not affect tumor growth in the absence of treatment in these models." (PMID 32457312, 2020). "To investigate if BRD9 inhibition can also affect other nonoverlapping CSC populations, we used flow cytometry analyses of CSC marker expression in PDAC cell lines and PDAC patient-derived primary tumor samples." (PMID 37739089, 2024).
hematological malignancies (7 papers, 2019 to 2025). "In a GDSC query assessing I-BRD9 sensitivity across 958 cell lines, the cell lines susceptible to BRD9 inhibition were predominantly from hematological malignancies (89% compared to the expected 17%), notably including CLL." (PMID 39261602, 2024). "Bromodomain-containing protein 9 (BRD9) was recently found to be important for the maintenance of the transformed phenotype of various hematological malignancies." (PMID 38610997, 2024). "In the present study we identify BRD9 as a key regulator of AML tumorigenesis and offer new insights into the role of BRD9 in hematological malignancies." (PMID 31000698, 2019). "BRD9 depletion alters transcriptional programs and induces apoptosis in hematologic malignancies." (PMID 41488087, 2025). "Our findings indicate that the degradation of BRD9 results in significantly greater effects compared to bromodomain inhibitors, as seen in AML as well in other hematologic malignancies." (PMID 35853853, 2022). "We find that modulating BRD9 potentiates the effects of numerous agents that are currently part of the standard treatment regimen for AML and other hematologic malignancies to induce differentiation and/or cytotoxic outcomes." (PMID 35853853, 2022). "Bromodomain-containing protein 9(BRD9), a component of the noncanonical BAF complex responsible for chromatin remodeling, has been recognized as an appealing therapeutic target in hematological malignancies." (PMID 38256933, 2024). "Bromodomain-containing protein 9 (BRD9), a component of non-canonical BAF chromatin remodeling complex, has been identified as a critical therapeutic target in hematological diseases." (PMID 36918560, 2023).
infection (3 papers, 2021 to 2023). The state of being infected such as from the introduction of a foreign agent such as serum, vaccine, antigenic substance or organism. "Taken together, the anti-inflammatory effect of BRD9 deletion or degradation in bone tissue is likely more prominent under infection stimulated circumstance compared within the basal condition." (PMID 36918560, 2023). "Therefore, our data should also raise awareness that, in such applications, drugs targeting BRD9 may have the undesirable side effect of limiting the effectiveness of endogenous host innate antiviral IFN responses, thereby potentially increasing the susceptibility of individuals to some infections." (PMID 34397140, 2021). "Notably, treatment of A549 cells with siRNAs that target BRD9 or GLTSCR1, but not BRD7 or ARID2, led to a reproducible (although not statistically significant) reduction in the ability of IFN‐α2 to fully protect cells from infection with the IFN‐sensitive vesicular stomatitis virus (VSV) (Fig EV1C)." (PMID 34397140, 2021).
adenocarcinoma (2 papers, 2022 to 2024). A common cancer characterized by the presence of malignant glandular cells. "Publicly available data revealed that Survival Probability was significantly worse in CRC cancer patients for whom BRD9 transcript expression was high in adenocarcinomas as compared with those harboring relatively low BRD9 levels." (PMID 36297001, 2022).
infectious disease (1 paper, 2022). A disorder directly resulting from the presence and activity of a microbial, viral, or parasitic agent in humans. "However, future efforts to predict and elucidate the impact of BRD9 missense variants on human susceptibility to infectious diseases should probably prioritize ultra-rare BRD9 variants, including severely truncated LOF variants." (PMID 36100643, 2022).
BRD9 also shares sentences with these, for which no sentence is quoted: colon adenocarcinoma (4 papers); bladder cancer (3); esophageal cancer (3); acute lymphoblastic leukemia (2); diabetes (2); Ewing sarcoma (2); gastric cancer (2); acute monocytic leukemia (1); acute periodontitis (1); adrenocortical carcinoma (1); anaplastic thyroid carcinoma (1); benign tumors (1); blood cancers (1); brain cancer (1); breast invasive carcinoma (1); cholangiocarcinoma (1); colon adenoma (1); colorectal (1); cutaneous squamous cell carcinoma (1); endocervical adenocarcinoma (1); eosinophilic leukemia (1); epidermoid carcinoma (1); erythroleukemia (1); essential thrombocythemia (1); Fibroids (1); glioblastoma (1); head and neck squamous cell carcinoma (1); hematologic cancer (1); Hyperglycemia (1); lipid metabolism disorders (1).
A further 26 diseases each share a sentence with BRD9 in 1 paper.